SPAG9 (sperm associated antigen 9)
Diseases named in the same sentence as SPAG9 in open-access papers (continued):
Sharing a sentence is not in itself a finding about the gene and the disease.
astrocytoma (3 papers, 2015 to 2024). "Interestingly, in our study, one of the two sequenced affected individuals carrying the SPAG9 variant in Family L had a Grade II astrocytoma." (PMID 25652157, 2015). "Our analyses revealed that SPAG9 carried a de novo PTV in our cohort and it is reportedly overexpressed in human astrocytoma which arises from neural progenitor cells in the central nervous system." (PMID 33860439, 2021).
endometrial cancer (3 papers, 2013 to 2024). Primary or metastatic malignant neoplasm involving the endometrium (mucous membrane that lines the endometrial cavity). "Nowadays, it is possible to speculate its role as a marker for progestin resistance, but the following affirmative studies are needful to prove the role of SPAG9 in the endometrial cancer because of the small number of the cohort analyzed in this study." (PMID 36203482, 2022).
hepatocellular carcinoma (3 papers, 2016 to 2024). A malignant tumor that arises from hepatocytes. "The aberrant expression of sperm-associated antigen 9 (SPAG9) is associated with numerous cancers, including hepatocellular carcinoma (HCC)." (PMID 26790956, 2016).
renal fibrosis (3 papers, 2020 to 2025). A final common manifestation of a wide variety of chronic kidney diseases characterized by glomerulosclerosis and tubulointerstitial fibrosis. "In vivo, SPAG9 overexpression or stimulation mitigated renal fibrosis, whereas low SPAG9 levels correlated with more severe fibrosis." (PMID 40149956, 2025).
squamous cell carcinoma (3 papers, 2013 to 2022). A carcinoma arising from squamous epithelial cells. "The other 10 patients diagnosed with squamous cell carcinoma grade II or grade III also expressed SPAG9 but with varying intensity." (PMID 34493268, 2021).
bladder cancer (2 papers, 2013 to 2024). "Further, SPAG9 association with malignant properties acquisition is suggestive of its possible role in acquisition of the invasive phenotype of bladder cancer and warrants further studies." (PMID 24349057, 2013). "In order to investigate the potential role of SPAG9 in bladder tumorigenesis, we further investigated the SPAG9 expression in various bladder cancer cells of different histotypes." (PMID 24349057, 2013). "Gene silencing approach was employed to knockdown the SPAG9 expression in high-grade invasive bladder cancer cell UM-UC-3." (PMID 24349057, 2013). "In addition, effect of SPAG9 gene silencing on cellular proliferation, cell cycle, invasion and migration was assessed in highly invasive bladder cancer cell line, UM-UC-3." (PMID 24349057, 2013). "Interestingly, our flow cytometric data analysis revealed that all bladder cancer cells showed cell surface localization of SPAG9." (PMID 24349057, 2013). "SPAG9 expression was observed in all bladder cancer cell lines of different histological types." (PMID 24349057, 2013). "In addition, we investigated the effect of SPAG9 ablation on cellular proliferation, cell cycle, migration and invasion in UM-UC-3 bladder cancer cells by employing gene silencing approach." (PMID 24349057, 2013). "Therefore, we investigated the effect of SPAG9 knockdown on cellular proliferation, migration and invasion in high grade invasive bladder cancer cell UM-UC-3." (PMID 24349057, 2013). "The fact that siRNA against SPAG9 inhibit cancer cellular proliferation, migration and invasion of bladder cancer cells suggests that SPAG9 expression may be involved in early spread and progression of bladder cancer." (PMID 24349057, 2013). "All four bladder cancer cell lines revealed SPAG9 expression." (PMID 24349057, 2013). "Four bladder cancer cell lines were assessed for SPAG9 expression." (PMID 24349057, 2013). "Thus, SPAG9 could be a potential biomarker and therapeutic target for better management of the bladder cancer patients." (PMID 24349057, 2013).
cataract (2 papers, 2025). Partial or complete opacity of the crystalline lens of one or both eyes that decreases visual acuity and eventually results in blindness. "For the firsttime in the literature, biallelic SPAG9 gene variation waslinked to multisystem-exhibiting features like coarse facial features, albinism,cataracts, skeletal abnormalities, and developmental delay." (PMID 39846792, 2025).
glioma (2 papers, 2015 to 2022). A benign or malignant brain and spinal cord tumor that arises from glial cells (astrocytes, oligodendrocytes, ependymal cells). "The non-synonymous SPAG9 variant identified in our study contributes to existing evidence that this gene may play an important role in glioma susceptibility." (PMID 25652157, 2015).
liver cancer (2 papers, 2021 to 2022). An epithelial or non-epithelial malignant neoplasm that arises from the liver. "Some reports have found that miR-141 can inhibit the proliferation of liver cancer cells by targeting sperm-associated antigen 9 (SPAG9), hepatocyte nuclear factor 3β (HNF 3β), zinc finger E-box (ZEB1), and so on." (PMID 34675977, 2021).
triple-negative breast carcinoma (2 papers, 2013 to 2021). An invasive breast carcinoma which is negative for expression of estrogen receptor (ER), progesterone receptor (PR), and human epidermal growth factor receptor 2 (HER2). "Collectively, our data has laid foundation for SPAG9 to be used as a potential therapeutic target for triple-negative breast cancer." (PMID 24330581, 2013). "Employing plasmid-based small interfering RNA (siRNA) approach, knockdown of SPAG9 was carried out in triple-negative breast cancer cells, MDA-MB-231, to assess its role on various malignant properties in vitro and in vivo." (PMID 24330581, 2013). "Therefore, in the present study, we assessed the role of SPAG9 in triple-negative breast cancer cells." (PMID 24330581, 2013). "In summary, our data indicated that down regulation of SPAG9 reduces growth and invasive potential of triple-negative breast cancer cells, suggesting that SPAG9 may be a potential target for therapeutic use." (PMID 24330581, 2013).
viral infection (2 papers, 2020 to 2022). "We then investigated the roles of SPAG9 in apoptosis, necroptosis, and pyroptosis upon viral infection." (PMID 35638835, 2022).
adrenocortical carcinoma (1 paper, 2023). "In all the tumor types except for ccRCC, SPAG9 was significantly correlated with OS in adrenocortical carcinoma (ACC), BLCA, and kidney chromophobe carcinoma (KICH), and it was a risk factor." (PMID 37107702, 2023).
albinism (1 paper, 2025). A congenital disorder characterized by partial or complete absence of melanin pigment in the eyes, hair, or skin. "In conclusion, to our knowledge, this is the first time to define the phenotypicspectrum of SPAG9-associated with coarse facial features, albinism,cataract, skeletal abnormalities, and developmental delay." (PMID 39846792, 2025).
bladder tumors (1 paper, 2013). "In addition, SPAG9 expression was detected in 80% patients with low grade and 81% patients with high grade bladder tumors." (PMID 24349057, 2013).
cervical squamous cell carcinoma (1 paper, 2021). A squamous cell carcinoma arising from the cervical epithelium. "Stage wise distribution of SPAG9 was analyzed in 281 samples of cervical squamous cell carcinoma and endocervical adenocarcinoma (CESC) from the cancer genome atlas data (TCGA)." (PMID 34493268, 2021).
Cirrhosis (1 paper, 2021). A chronic disorder of the liver in which liver tissue becomes scarred and is partially replaced by regenerative nodules and fibrotic tissue resulting in loss of liver function. "For instance, the levels of anti-sperm-associated antigen 9 (SPAG9) antibodies were significantly higher compared with those in patients with hepatitis/cirrhosis or healthy controls." (PMID 33672007, 2021).
COVID-19 (1 paper, 2020). A disease caused by infection with severe acute respiratory syndrome coronavirus 2. "In addition, it is likely that a combination of RPS29 and SPAG9 genes induced pathways, as well as downregulation of cardioprotective genes, contribute to cardiac and vascular events in patients with COVID-19." (PMID 33240937, 2020).
developmental delay (1 paper, 2025). "Our studysuggests SPAG9 gene as a strong candidate for oculocutaneousalbinism, developmental delay, cataract and coarse facial features due to loss offunction variant (LOF), however further evidences in humans are needed." (PMID 39846792, 2025).
melanoma (1 paper, 2023). A malignant, usually aggressive tumor composed of atypical, neoplastic melanocytes. "Immunoprecipitation studies confirmed the association of HLA-G with SPAG9 in lung and melanoma BMICs." (PMID 36780531, 2023). "Surprisingly, we noticed an increase in SPAG9 protein levels in HLA-G OE lung and melanoma BMICs compared to their respective controls." (PMID 36780531, 2023). "We also observed reduced SPAG9 expression in HLA-G-depleted lung and melanoma BMICs, indicating a positive correlative relationship between HLA-G and SPAG9 in BMICs." (PMID 36780531, 2023). "Nonetheless, we found that SPAG9 ablation in HLA-G OE lung and melanoma BMICs diminished the expression of p-STAT3 despite the high HLA-G levels present in these cells, demonstrating that HLA-G modulates STAT3 signaling in BMICs via SPAG9." (PMID 36780531, 2023). "To elucidate whether HLA-G stimulates STAT3 signaling in BMICs via SPAG9, we generated pooled SPAG9 knockout in HLA-G OE lung BMICs and probed for the expression of p-STAT3 (Y705) in control and SPAG9 knockout lung and melanoma BMICs." (PMID 36780531, 2023).
mucinous carcinoma (1 paper, 2024). "A report showed high frequency of SPAG9 (CT89) mRNA in serous carcinoma (88%), mucinous carcinoma (100%), and transparent carcinoma (100%), respectively." (PMID 38896069, 2024).
myocarditis (1 paper, 2020). Myocarditis is a condition that is characterized by inflammation of the heart muscle (myocardium). "The virus-induced upregulation of SPAG9 might induce antibodies against it that might cross-react with the heart cytoskeleton and cause cardiac damage in the form of myocarditis and cardiac dysfunction." (PMID 33240937, 2020).
tumor (27 papers, 2013 to 2024). "We had previously evaluated small-scale DC production in vitro, and compared autologous tumor lysate-primed DCs with recombinant human sperm-associated antigen 9 (rhSPAG9)-primed DCs." (PMID 38400096, 2024). "The SPAG9 expression was associated with a poor prognosis in pan-cancer patients, but with a good prognosis and slow tumor progression in ccRCC patients." (PMID 37107702, 2023). "Reduced SPAG9 expression was significantly associated with clinical-stage progression (Stage I vs. Stage IV), primary tumor enlargement (T1 vs. T4), and tumor metastasis (N0 vs. N1 and M0 vs. M1) in the ccRCC patients (p value < 0.05)." (PMID 37107702, 2023). "Sperm-associated antigen 9 (SPAG9) is a cancer-testis antigen expressed in various tumor tissues, which has two main alternative spliceosomes—JLP (1307 amino acids) and SPAG9 (766 amino acids)." (PMID 37107702, 2023). "SPAG9 is a scaffold protein that organises mitogen-activated protein kinases and has been associated with invasion in several types of tumours and prognosis." (PMID 33845831, 2021). "By analyzing the scRNA-seq data of the ccRCC patients, we found that the key genes were highly expressed in the tumor stromal cells (endothelial cells), which was consistent with the previous finding that SPAG9 expression was significantly associated with OS only in the stroma-rich group." (PMID 37107702, 2023). "Furthermore to investigate whether SPAG9 siRNA treated animals which showed reduced tumor growth was associated with reduced cellular proliferation, serial tumor sections were probed for PCNA expression." (PMID 24330581, 2013). "The percentage of tumor cells positive for SPAG9 was assessed, and a cut-off of >20% was designated based on SPAG9 expression in the normal cervix tissue (n = 5)." (PMID 38400096, 2024). "We summarized the roles of SPAG9 in tumor-cell lines and noted that in addition to promoting proliferation, migration, and EMT, SPAG9 also promotes autophagy in several tumor-cell lines." (PMID 37107702, 2023). "We noted that in addition to promoting proliferation, migration, and EMT, SPAG9 also promotes autophagy in several tumor-cell lines." (PMID 37107702, 2023). "Previous studies showed that autophagy activation inhibited tumor progression by suppressing the inflammatory response, so we investigated the relationship between SPAG9 and the inflammatory response in ccRCC and BLCA." (PMID 37107702, 2023). "It was reported that SPAG9 promotes proliferation and migration in many tumor-cell lines, including the ccRCC cell lines Caki-1 and NII-AKS413." (PMID 37107702, 2023). "We carefully reviewed previous studies on the role of SPAG9 in different tumor-cell lines and summarized the results." (PMID 37107702, 2023). "Through further analyses, we found that the correlation between SPAG9 expression and ccRCC prognosis was dependent on the tumor stroma." (PMID 37107702, 2023). "Silencing the expression of SPAG9 in triple-negative breast cancer and liver cancer effectively inhibited the proliferation and migration of tumor cells." (PMID 35535313, 2022). "SPAG9 is highly expressed in various malignant tumor tissues such as PCa, renal cancer, breast cancer, bladder cancer, and lung cancer." (PMID 35535313, 2022). "Six have been indirectly linked to tumour malignancy and are thus new splicing targets to study (CAST, CSF1, PLOD2, SLK, SPAG9, TSC2)." (PMID 33845831, 2021). "SPAG9 is as good as tumor lysates and can be used for DCs pulsing for further experiments or clinical trials." (PMID 34493268, 2021). "Our results showed that knockdown of linc00483 inhibited tumour growth, increased miR‐30a‐3p levels, and decreased both SPAG9 and c‐Jun protein levels in the xenograft model." (PMID 29761936, 2018). "Recently, SPAG9 overexpression was identified to be correlated with poor prognosis and tumor progression in human HCC." (PMID 26790956, 2016).
tumor (continued). "Previous studies have shown that the expression of SPAG9 was elevated in a variety of malignancies and correlated with tumor stage and prognosis, including HCC." (PMID 26790956, 2016). "Since c-Jun and MMP9, which are a major downstream molecule and a target gene in the JNK pathway, were reported to play important roles in JNK-mediated tumor growth and metastasis, we further examined the effect of miR-141 and SPAG9 on these gene expressions." (PMID 26790956, 2016). "In the present study, we also found that the downregulation of miR-141 in HCC and the expression patterns of SPAG9 were inversely correlated with those of miR-141 in HCC tumor samples and cell lines." (PMID 26790956, 2016). "A representative photograph shows reduced tumor growth in SPAG9 siRNA treated group compared with control siRNA treated group." (PMID 24330581, 2013). "Our in vitro data indicated that ablation of SPAG9 expression by SPAG9 siRNA significantly reduced colony formation which led us to investigate its effect on human breast xenograft tumor growth in nude mice in vivo." (PMID 24330581, 2013). "Subsequently, cell specific SPAG9 gene expression was determined by employing in situ RNA hybridization in serial sections of different tumor stages." (PMID 24349057, 2013). "The tumor volume of mice injected with SPAG9 siRNA showed a significant reduction in tumor growth as compared to mice administered with control siRNA (P < 0.001)." (PMID 24330581, 2013). "All the tumor tissue specimens found positive for SPAG9 mRNA were also found positive for SPAG9 protein expression." (PMID 24349057, 2013). "Representative photomicrographs of bladder TCC serial sections showed cytoplasmic localization of SPAG9 protein in tumor cells of various stages." (PMID 24349057, 2013). "Our study found that SPAG9 expression predicted opposite clinical outcomes in pan-cancer and ccRCC patients, and we speculated that SPAG9 suppresses tumor progression by promoting autophagy and inhibiting inflammatory responses in ccRCC." (PMID 37107702, 2023). "Combined with a bioinformatics analysis and an experimental validation, we speculated that SPAG9 suppresses tumor progression by promoting autophagy and inhibiting inflammatory responses in ccRCC." (PMID 37107702, 2023). "We further found that some genes might cooperate with SPAG9 to promote autophagy, and that these were highly expressed in the tumor stroma and may be key genes." (PMID 37107702, 2023). "We further found that some genes might cooperate with SPAG9 to promote autophagy, and that these were highly expressed in the tumor stroma and could be represented by key genes." (PMID 37107702, 2023). "In conclusion, we speculated that in the tumor stroma, some genes cooperate with SPAG9 to promote autophagy, and that these may be key genes, which can be represented by the key genes." (PMID 37107702, 2023). "Interestingly, a higher antibody response against SPAG9 was observed in cancer patients, suggesting its therapeutic potential as a tumor immunotherapy target." (PMID 32776977, 2020). "Furthermore, a volcano plot analysis of the entire dataset with MG vs Non-tumor controls revealed significant upheaval in proteins like SPAG9, NDRG2." (PMID 32974197, 2020). "Furthermore, SPAG9 restoration in miR-141-expressing cells sufficiently attenuated the tumor-suppressive effects of miR-141." (PMID 26790956, 2016). "The down-regulation of SPAG9 by siRNA approach could also inhibit tumor cell proliferation and invasion." (PMID 26790956, 2016). "This inverse correlation of SPAG9 expression and disease progression might suggest that SPAG9 is required in early spread of tumor progression, when cells acquire the malignant properties such as cellular proliferation, invasion and migration." (PMID 24349057, 2013). "SPAG9 protein validation was carried out on serial sections of tumor specimens by IHC." (PMID 24349057, 2013).